SPIC (Spi-C transcription factor)
Description:
Controls the development of red pulp macrophages required for red blood cells recycling and iron homeostasis. Transcription factor that binds to the PU-box, a purine-rich DNA sequence (5'-GAGGA[AT]-3') that can act as a lymphoid-specific enhancer. Regulates VCAM1 gene expression (By similarity).
Synonyms: MGC40611; SPI-C
Tractability: No criterion of Open Targets' tractability assessment is met for any kind of drug.
Gene: Protein-coding gene on chromosome 12 (101,475,336 to 101,486,997, forward strand). Ensembl gene ENSG00000166211.
Subcellular location: Nucleus
Gene Ontology:
Molecular function: protein binding; DNA-binding transcription factor activity, RNA polymerase II-specific; DNA-binding transcription activator activity, RNA polymerase II-specific; DNA-binding transcription factor activity; RNA polymerase II cis-regulatory region sequence-specific DNA binding; sequence-specific DNA binding
Biological process: cell differentiation; regulation of transcription by RNA polymerase II; positive regulation of transcription by RNA polymerase II; regulation of DNA-templated transcription
Cellular component: chromatin; nucleus
Genetic constraint (gnomAD): Loss-of-function variants: 5 observed, 9.63 expected, observed/expected ratio (o/e) 0.52, 90% interval 0.27 to 1.09. That is too few expected variants to judge how well the gene tolerates losing a copy. Missense variants: 228 observed, 275.87 expected, observed/expected ratio (o/e) 0.83, 90% interval 0.74 to 0.92. Synonymous variants: 92 observed, 97.13 expected, observed/expected ratio (o/e) 0.95, 90% interval 0.8 to 1.13.
Homologues: Orthologues: chimpanzee SPIC (99% identical), pig SPIC (89% identical), dog SPIC (88% identical), rat Spic (72% identical), mouse Spic (66% identical), guinea pig SPIC (62% identical), tropical clawed frog SPIC (48% identical), zebrafish spic (42% identical). Paralogues in human: SPI1 (31% identical), SPIB (28% identical), ELF1 (21% identical), ELF4 (20% identical), ETS2 (20% identical), ELF2 (19% identical), ETV6 (19% identical), ETS1 (19% identical), ETV7 (19% identical), FLI1 (19% identical), SPDEF (18% identical), EHF (17% identical), and 16 more.
Diseases named in the same sentence as SPIC in open-access papers:
SPIC is named in the same sentence as 16 diseases in open-access papers, as found by Europe PMC text mining. Sharing a sentence is not in itself a finding about the gene and the disease. The quoted sentences say what the papers report.
parasitemia (2 papers, 2012 to 2025). "For example, splenic monocytes are capable of phagocytosis of P. chabaudi, and this population undergoes expansion near the time of peak parasitemia in both SpiC+/− and SpiC−/− mice." (PMID 23144737, 2012). "Surprisingly, the course of rising and falling parasitemia in SpiC− /− mice occurred with kinetics essentially identical to the course in SpiC+/− animals and wild type C57BL/6 animals." (PMID 23144737, 2012). "In contrast, Ly6clo monocyte frequencies were increased in the blood of SpiC−/− mice during resolution of peak parasitemia (days 9 and 12), and were significantly higher in spleens of SpiC−/− mice throughout infection (p = 0.02, Wilcoxon matched pairs signed-rank test)." (PMID 23144737, 2012).
breast carcinoma (1 paper, 2020). "Associations between CLCA2, SPIC, and MIR4311 and overall and breast cancer specific survival in the Detroit AA cohort." (PMID 32298355, 2020). "Three genes (CLCA2, SPIC, MIR4311) were associated with overall and breast cancer specific survival in this discovery cohort." (PMID 32298355, 2020).
melanoma (1 paper, 2025). A malignant, usually aggressive tumor composed of atypical, neoplastic melanocytes. "In melanoma, several ETS TFs, including FLI1, SPI1, ELF4, ETV7, SPIB, and SPIC, are expressed at higher levels in Cluster A patients, whereas ETV5, ETV4, ELK1, ERF, and ETV2 showed increased expression in Cluster B patients." (PMID 41502516, 2025).
periodontitis (1 paper, 2023). An acute or chronic inflammatory process that affects the tissues that surround and support the teeth.
Salmonella Infections (1 paper, 2009). Infections with bacteria of the genus SALMONELLA. "Additionally, our recent study shows that SpiC is involved in the expression of FliC, a component of the flagella filaments, where FliC plays a significant role in SpiC-dependent activation of the signal transduction pathways in macrophages following Salmonella infection." (PMID 19706157, 2009).
infection (11 papers, 2010 to 2025). The state of being infected such as from the introduction of a foreign agent such as serum, vaccine, antigenic substance or organism. "We also measured changes in the labile iron pool during infection with two isogenic mutant Salmonella strains, spiA and spiC, which have intracellular trafficking deficits associated with reduced intracellular proliferation and avirulence in mice." (PMID 20184753, 2010). "Salmonella pathogenicity is mediated by numerous genes such as invA, spiC and pipD, which code for effectors that induce successful host infection." (PMID 31405078, 2019). "Wild-type Salmonella harbouring a transcriptional fusion of the spiC promoter to a promoter-less gfp gene in plasmid pFPV25 showed high levels of spiC expression 6 h after infection." (PMID 31440219, 2019). "Since Salmonella pathogenicity is determined by genes which work collaboratively for successful infection, invA, iroB, spiC and pipD were screened from the isolates." (PMID 31405078, 2019). "Detailed examination of monocyte frequencies on day 12 post-infection confirmed that Ly6clo monocytes were significantly elevated in both blood and spleens of SpiC−/− mice." (PMID 23144737, 2012). "After 24 h infection with P. chabaudi, SpiC−/− mice produced roughly half the splenic IFNB of SpiC+/−mice, with similar results also observed in plasma." (PMID 23144737, 2012). "After PspiC and PssaG strains were orally infected into mouse ileal loops, SpiC protein could also be detected at 15 min post infection." (PMID 31440219, 2019). "The conclusions showed that the loss of spiC did not change the virulence of Salmonella Typhimurium and the lethality of infection in Caenorhabditis elegans because of the similar rate of death with the wild-type Salmonella group." (PMID 31440219, 2019). "SpiC cannot be detected until approximately 1 h after infection." (PMID 31440219, 2019). "The intramacrophage survival of the spiC-deleted mutant of Salmonella Typhimurium 14028s was less than 20% compared with 100% of wild-type Salmonella Typhimurium 14028s in J774 macrophages at 18 h post infection." (PMID 31440219, 2019). "SpiC is expressed during all stages of infection by T3SS2 and spiC gene usually represents T3SS2 in the literature; however, SpiC/SsaB is secreted in the early stages of SCV biogenesis (<30 min) by T3SS1." (PMID 31440219, 2019). "Given that at 144 hpi we were able to detect all mutant strains on liver, and the REROD21 was near to 1 in this organ, we evaluated the expression of invA, sipB, spiA, spiC and ROD21 genes at this time post-infection." (PMID 31800631, 2019).
tumor (2 papers, 2024 to 2025). "SPIC and MAFB were predominantly expressed in normal and adjacent tissues, while SPP1+ TAM-associated TFs (SREBF1, JUN, SPI1, and CREB1) showed peak expression in tumor core regions." (PMID 40725473, 2025).
cancer (1 paper, 2025). A tumor composed of atypical neoplastic, often pleomorphic cells that invade other tissues. "Second, we uncover the following important genes: KIF18A, PABPC1, and SPIC, which are consistent with previous cancer studies." (PMID 40286292, 2025).
SPIC also shares sentences with these, for which no sentence is quoted: atherosclerosis (1 paper); bacteremia (1); colitis (1); hemophagocytic lymphohistiocytosis (1); iron overload (1); leukemia (1); lymphoma (1); Splenomegaly (1).